FGF19 (fibroblast growth factor 19)
Diseases named in the same sentence as FGF19 in open-access papers (continued):
Sharing a sentence is not in itself a finding about the gene and the disease.
tumor (continued). "To assess the translational relevance and clinical significance of our findings, we systematically examined association between FGF19 expression and STAT3 activation in primary tumours from the Cancer Genome Atlas (TCGA) database, and in formalin-fixed, paraffin-embedded or frozen human HCC samples." (PMID 28508871, 2017). "Furthermore, the FGF19-induced tumours observed to develop in Stat3f/f mice were highly proliferative, as demonstrated by immunohistochemical staining with antibodies against Ki-67." (PMID 28508871, 2017). "Moreover, FGF19 and BIRC5 were concomitantly overexpressed in all 10 of these tumour samples, further establishing a positive correlation between the expression of FGF19 and BIRC5, a STAT3 target gene, in human HCC." (PMID 28508871, 2017). "However, the liver-enriched receptor FGFR4 is also thought to mediate the tumorigenic effects of FGF19, since inactivation of FGFR4 via gene knockout or a neutralizing antibody reduces the tumour burden in FGF19 transgenic mice." (PMID 28508871, 2017). "Importantly, FGFR4/FGF19 co-expression was associated with AKT phosphorylation (P < 0.001), Ki-67 staining (P = 0.005) and higher tumor stage (P < 0.001)." (PMID 27192118, 2016). "FGF19 has been reported to be secreted from multiple cell types within the tumor microenvironment and functioned as both autocrine and paracrine factors on tumor cells and stromal cells." (PMID 26498355, 2016). "It appears that a subset of tumours is driven by the FGF19/FGFR4 pathway and these patients could benefit from treatment with FGFR4 inhibitors." (PMID 28943626, 2015). "Interestingly, ligands for this receptor, FGF2, FGF17, FGF8, and FGF19, were also overexpressed in the tumour." (PMID 26998479, 2015). "These activities of FGF21 and possibly FGF19 on adipocytes that elicit tumor suppressive metabolic signals appear sufficient to override tumor-promoting effects of elevated bile acids, inflammation and mild metabolic abnormalities elicited by the FGFR4 deficiency." (PMID 24279986, 2013). "The sensitivity of serum FGF19 thus makes it a promising tumor marker for HCC." (PMID 23776502, 2013). "1A6 was previously shown to prevent tumor formation in FGF19-TG mice." (PMID 22615798, 2012). "Results of the invasion assay and migration assay indicate that FGF19 may be an activator of tumor metastasis." (PMID 22309595, 2012). "Because FGF19-7 does not induce hepatocyte proliferation, it could be used as a tool to test the link between BrdU incorporation observed by acute FGF19 treatment in a 1-week study to the long term effect of tumor development." (PMID 22457778, 2012). "Taken together our results identify AR as a new downstream target of FGF19 in HCC cells, and reveal a functional cross-talk in which the AR/EGFR system could mediate, and likely amplifiy, the tumor-promoting effects of FGF19." (PMID 23285165, 2012). "In addition, we also examined the expression of AR and FGF19 in the two subclasses of tumours with differential prognosis that were identified in the GSE1989 data set according to their gene expression profiles." (PMID 23285165, 2012). "In order to investigate further whether FGF19 plays an important role in tumor metastasis, the invasion assay and migration assay were performed." (PMID 22309595, 2012). "The sensitivity of serum FGF19 renders it a promising tumor marker for HCC." (PMID 22309595, 2012). "Interestingly, we found that the expression of AR and FGF19 genes was higher in the subclass of tumours with strong cell proliferation and anti-apoptosis gene expression signatures, corresponding to patients with poorer prognosis (reduced survival)." (PMID 23285165, 2012). "Hence, the balance between glycolysis and oxidative phosphorylation in tumor cells might be influenced by FGF19, potentially shifting metabolic preference toward more efficient energy production." (PMID 41328353, 2026).
tumor (continued). "It elucidates the intercellular interactions of FGF19 within the tumor microenvironment, suggesting that it may influence the progression of CRC and the regulation of the immune microenvironment by affecting the functions and interactions of these key immune cells." (PMID 41328353, 2026). "We identified CD36, MMP1, TGFBR3, TWIST2, ITGB1, and FGF19 as associated with poorer outcomes: CD36 enhances tumour stemness and growth, MMP1 facilitates metastasis, TGFBR3 and TWIST2 promote EMT and invasion, ITGB1 supports cell adhesion and survival, and FGF19 drives proliferation." (PMID 41007296, 2025). "In particular, we found that NPC-derived FGF19 could enhance tumour angiogenesis." (PMID 37782406, 2024). "Aberrant activation of FGF19 might contribute to neoplasia development." (PMID 37782406, 2024). "The result indicated FGF19 expression was much higher in CRC than nontumor tissues, and FGF19 had a positive association with worse tumor differentiation, more frequent lymph node metastasis, an increased incidence of distant metastasis and higher AJCC staging." (PMID 36923538, 2023). "In addition, higher levels of Vimentin were consistently seen in tumor tissues derived from knockdown control MT-LE cells compared with knockdown control parental cells, which were dramatically suppressed in xenograft tumors when FGF19 was depleted." (PMID 33691750, 2021). "A high level of FGF19 in a tumor may serve as a potential biomarker for patient selection." (PMID 33235319, 2020). "In addition to the downregulation of FGF19 to demonstrate the anti-cancer effect that was also shown in other cancer models, herein we demonstrated for the first time that overexpressing FGF19 promoted tumor cell proliferation and metastasis in vivo in LSQ." (PMID 32111983, 2020). "Moreover, FGF401 inhibits tumor xenografts that express FGF19, FGFR-4, and Klotho-β19." (PMID 33235319, 2020). "However, the therapeutic potential of FGF19 has been hindered by its effect on potential occurrence of HCC, since mice expressing an FGF19 transgene developed liver tumors while tumor FGF19 hepatic mRNA expression was an independent prognostic factor for overall and disease-free survival." (PMID 32823659, 2020). "We next examined whether FGF19 could play a role in tumor metastasis." (PMID 32111983, 2020). "Therefore, immunostaining for tumor FGF19 or measuring serum FGF19 could be a valuable and practical method for identifying patients with HCC who will likely respond to FGF401." (PMID 33235319, 2020). "Therefore we propose that a simultaneous increase of FGF19/FGFR4 associated with an increased level of EpCAM may help to identify which patients may have a more aggressive and resistant tumor biology requiring multi-drug therapy." (PMID 27447573, 2016). "Within the tumor microenvironment of HCC, FGF19 is primarily expressed by cancer cells; however, it can also be secreted and affect surrounding stromal cells." (PMID 41328353, 2026). "FGF19 derived from NPC cells stimulates angiogenesis both in vivo and in vitro, which is a pivotal factor for tumor growth and metastasis." (PMID 41328353, 2026). "This combined therapy works by inhibiting the FGFR2/3 and FGF19/FGFR4 signaling pathways, thereby curbing tumor cell proliferation and inducing apoptosis." (PMID 41328353, 2026). "In the context of HCC, FGF19, the ligand for FGFR4, is frequently amplified and overexpressed, leading to the activation of the FGFR4 signalling pathway and contributing to tumour development and progression." (PMID 41503573, 2026). "In BC research, transfection with specific siRNA to silence the FGF19 gene can effectively block the signaling between FGF19 and FGFR4, inhibiting the proliferation and migration of tumor cells." (PMID 41328353, 2026). "The crosstalk between FGF19 and the JAK-STAT pathway is a crucial link that further elucidates the complex signaling network driving tumor progression." (PMID 41328353, 2026).
tumor (continued). "The interplay between FGF19, the PI3K/AKT signaling pathway, and GLUT1 is extremely crucial in tumor metabolism and significant in cancer progression and treatment." (PMID 41328353, 2026). "Expression of FGF19 is downregulated by lenvatinib, a multi-target drug, in CCA cells, thereby inactivating the PI3K/AKT pathway and inhibiting tumor cell proliferation, migration, and invasion." (PMID 41328353, 2026). "The interaction between FGF19 and the ERK/MAPK pathway can enhance the mitogenic and oncogenic potential of tumor cells." (PMID 41328353, 2026). "In PDAC, the high expression levels of FGF19 and HMGA1 together define a tumor subtype characterized by an extremely poor prognosis." (PMID 41328353, 2026). "Mechanistically, FGF19 promotes EMT, a critical process for tumor invasion and dissemination, through FGFR4-mediated activation of key signaling pathways." (PMID 41002393, 2025). "FGF19, an endocrine FGF primarily involved in bile acid homeostasis under normal conditions, is often aberrantly elevated in CRC, contributing to tumor growth and metastasis." (PMID 41002393, 2025). "There were almost no FGF19-expressing cells that did not also express either AXIN2 or SOX4, suggesting that FGF19 expression is a unique feature of a subset of AXIN2+, SOX4+ tumor cells." (PMID 39567523, 2024). "We found that FGF19 overexpression was accompanied by MVD in both clinical NPC tissues and subcutaneous tumours." (PMID 37782406, 2024). "Analysis of signaling pathways by GSEA and gene expression analysis revealed that AZD4547-resistant tumor cells had enhanced c-Met signaling and higher FGF18 and FGF19 mRNA expression compared with AZD4547-sensitive cells." (PMID 38273381, 2024). "Previous studies have confirmed that ANXA2 influences tumour angiogenesis, and we then determined ANXA2 expression after FGF19 treatment." (PMID 37782406, 2024). "FGF19, belongs to the endocrine FGF family, acts as a signalling molecule and is overexpressed in a subgroup of tumours." (PMID 37782406, 2024). "FGF19, downstream of Wnt/β-catenin and SOX4, provides a requisite proliferative signal for surrounding tumor cells and promotes cell cycle progression together with constitutive Wnt activation." (PMID 39567523, 2024). "In this research, we discovered the importance of FGF19 in NPC, and clarified its role in tumour angiogenesis." (PMID 37782406, 2024). "Overall, this study demonstrated the potential of biogenic AgNPs for cancer treatment, while FGF19 and BCL-2 family chemicals showed great promise as tumor therapeutic targets or indicators of tumor disorders, providing hope for targeted tumor therapy." (PMID 39334936, 2024). "Intriguingly, in FGF19-silenced tumors, one E3LZ10.7 tumor at each dilution and one AsPC-1 tumor at the lowest dilution grew to proportions equal to or greater than controls." (PMID 36919699, 2023). "Intriguingly, FGF19 levels were much higher in the metastatic cell lines (E3LZ10.7 and AsPC-1) compared with MIA PaCa-2 cells derived from a localized tumor." (PMID 36919699, 2023). "Strikingly, there was a marked decrease in tumor volumes in mice treated with BLU9931, along with decreased staining for HMGA1, FGF19, Ki-67, and fibrosis (trichrome)." (PMID 36919699, 2023). "Previous finding demonstrates that FGF19 and FGFR4 are coexpressed in CRC and facilitate tumor growth." (PMID 36923538, 2023). "They comprehensively evaluated tumor secretory proteins to discover biomarkers for FGF19-driven HCC, identifying a correlation between FGF19 and the secretory protein ST6 β-galactoside α-2,6-sialyltransferase 1 (ST6GAL1) in HCC cells." (PMID 37686621, 2023). "In that study, it was observed that when the FGF19- FGFR4 interaction occurs in TAF, FGFR4 can phosphorylate β-catenin, which, in turn, can be translocated into the nucleus where can mediate the tumor-stroma interactions, facilitating the metastatic process." (PMID 34200439, 2021).
tumor (continued). "In FGF19+FGFR4+ HCC and FGF19−FGFR4− HCC groups, 39.4% and 23.1% of patients had vascular invasion or tumor satellite nodules, respectively." (PMID 33674622, 2021). "So, it is expected that overexpression of FGF19, β-klotho, and/or FGFR4 in tumor cells is related to the development and progression of HCC." (PMID 34200439, 2021). "The expression of FGF19 was similar to FGFR4 in more than half of the cases, and a significant correlation was noted between the expression of FGF19 and FGFR4 in tumor tissues (r = 0.601, p < 0.001)." (PMID 33674622, 2021). "In this tumor, we also observed not only upregulation of FGF ligands (FGF19 and FGF20; 88- and 68-fold, respectively) but also a very strong upregulation of the phospholipase PLA2G4A (345-fold)." (PMID 34271981, 2021). "The depletion of both FGF19 and FGFR4 increases the sensitivity of tumor cells to sorafenib, resulting in enhanced apoptosis and decreased viability." (PMID 33802841, 2021). "In detail, FGF1 and FGF10 were downregulated in most of the tumor types whereas FGF3, FGF5, FGF11, FGF19, FGF20, and FGF21 were upregulated in most of the tumor types." (PMID 32596330, 2020). "Recently, it has been proposed that FGF19 and KLB are potential biomarkers for prediction of early tumor recurrence in patients with resectable HCC." (PMID 32018226, 2020). "Treatment of mice bearing high FGF19-expressing HCC25-0705A tumors with 20, 30, and 40 mg/kg FGF401 twice a day led to 83.5%, 86.8, and 87% reductions in tumor burden, respectively (p < 0.0001)." (PMID 33235319, 2020). "Considering that FGF19 is a serum secretory protein produced by HCC cells in an autocrine loop fashion, we investigated the efficacy of serum FGF19 as a tumor marker." (PMID 31718608, 2019). "Here, we showed that lenvatinib inhibited tumor growth and suppressed the FGF signaling pathway in FGF19‐overexpressing HCC xenograft models." (PMID 29733511, 2018). "Emerging studies indicate a focal, high-level amplification frequency of FGF19 in HCC clinical samples, which is positively correlated with tumor size, pathological stage and poor prognosis." (PMID 28069043, 2017). "Recently, focal amplification frequency of FGF19 was identified in 12–14% of HCC clinical samples, which is positively correlated with tumor size, pathological stage and poor prognosis." (PMID 26498355, 2016). "The 11q13 amplicon contains Cyclin D1 which is a known oncogene but also FGF19, FGF23 and ANO1 which are tumour promoting genes." (PMID 28943626, 2015). "In HCC cells FGF19 signals through the FGFR4/β-klotho complex, which is also frequently up-regulated in human HCC tissues and is emerging as a good candidate anti-tumor target." (PMID 23285165, 2012). "FGF19 binds to FGF receptor 4 and has been shown to mediate cell cycle progression, angiogenesis and promote tumor growth through the beta-catenin pathway." (PMID 19948057, 2009). "Within the FGF19 transgenic HCC model, 1A6 treatment significantly reduced HCC incidence, with treated mice exhibiting minimal liver tumor formation, a substantial decrease in liver weight, and a reduction in tumor volume." (PMID 41328353, 2026). "Therefore, FGF19, through the modulation of the PI3K/AKT pathway and the indirect influence on GLUT1-mediated glucose metabolism, plays a key role in tumor metabolism and represents a promising target for cancer metabolism therapy." (PMID 41328353, 2026). "While its pro-tumor effects are documented, FGF19's utility as a blood serum marker for CRC is not well defined." (PMID 41631414, 2026). "Therefore, the interaction between FGF19 and EMT is of great significance for understanding the metastatic mechanisms of tumor cells." (PMID 41328353, 2026). "FGF19, FGF19-reaction (increase), Ang-2-Reaction (decrease), ST6GAL1, Tumor-FGFR4." (PMID 40164125, 2025). "The median PFS was longer for IHC FGF19-positive tumours (3.3 months) compared to IHC FGF19-negative tumours (2.3 months)." (PMID 40205008, 2025).
tumor (continued). "Early-phase trials of selective FGFR4 inhibitors (e.g., fisogatinib/BLU-554; roblitinib/FGF401) showed activity in FGF19-positive or FGFR4/KLB-positive tumours, validating pathway dependence but not yet yielding a registrational success." (PMID 41301037, 2025). "Given this condition, functionally blocking FGF19 and BCL-2 can restore tumor cell apoptosis." (PMID 39334936, 2024). "Although FGFR4 was expressed in fetal tumor organoids, FGF19 was not present in our culture medium, indicating that it was not essential for maintaining organoid culture in the presence of other growth factors." (PMID 39567475, 2024). "PI3K/AKT was reported to be activated by FGF19/FGFR4 and involved in tumour progression." (PMID 37782406, 2024). "Together, we discovered what we believe is a previously undescribed paradigm whereby tumor cells collaborate via HMGA1 and FGF19 to drive progression, thus illuminating FGF19 as a rational therapeutic target for a molecular subclass composed of the most aggressive human PDACs." (PMID 36919699, 2023). "Moreover, treatment with an FGF receptor 4 (FGFR4) inhibitor, BLU9931, to block FGF19 function recapitulates the effects of HMGA1 or FGF19 silencing, decreasing tumor growth and stroma formation in orthotopic models." (PMID 36919699, 2023). "Previous reports showed that db/db mice exhibited the shortest latency and higher tumor incidence among several tested mouse strains after AAV-mediated overexpression of FGF19, which provides a robust system to evaluate FGF19-induced hepatocarcinogenesis in vivo." (PMID 37789318, 2023). "Consistent with the FGF19/FGFR4 downstream pathway, tumor PD assessed by RNAseq revealed an upregulation of CYP7A1 transcript concomitant with downregulation of the MAPK target gene DUSP6, in most on-treatment biopsies obtained at C1D8 with respect to the matched pretreatment sample." (PMID 35655320, 2022). "It inhibits growth of HCC and gastric cancer cell lines expressing FGFR4, KLB and FGF19 with excellent selectivity over non-sensitive tumor models." (PMID 35655320, 2022). "FGF19 mediates cell escape from death by increasing the expression and phosphorylation of IL-6-induced STAT3, which is known to lead to compensatory proliferation in tumor cells." (PMID 33802841, 2021). "There were no noticeable changes in tumor growth in mice receiving FGF19 knockdown or its knockdown control cells after a four-week inoculation." (PMID 33691750, 2021). "No significant change in tumor cell proliferation or the percentage of cleaved PARP-positive cells was observed in low to undetectable FGF19-expressing HCC10-0505, HCC26-0808A, or HCC01-1214 tumors following FGF401 treatment." (PMID 33235319, 2020). "Evidence also shows downregulation of the FGF19/FGFR4 pathway could lead to decreased viability, invasion, and tumor formation of HCC in SCID mice." (PMID 32313144, 2020). "Treatment with 8 mg Lenvatinib did not lead to an increase in serum FGF19 levels (ratio 1.23) or a decrease in Ang-2 (ratio 1.24) levels at 4 weeks, and repeat CT scans showed marked tumor progression in the liver (progressive disease; PD) at 7 weeks (e)." (PMID 31991869, 2020). "Moreover, we detected 15 gene amplifications in six different tumor specimens, including AR, CCND1 (n = 2), FGF19 (n = 2), FGF3 (n =2), KRAS (n = 2), MYC (n = 2), CCND3, CCNE1, CDK6, and RICTOR." (PMID 33203166, 2020). "We found that downregulation of FGF19 inhibited the progression of tumor cells, whereas administration of AZD2014 did not further increase this inhibitory effect, both in tumor volume and Ki-67, p-AKT expression levels." (PMID 32111983, 2020). "As shown in our study, as long as KLB was overexpressed, tumor inhibition was observed regardless of the level of FGF19 in the cancer cells." (PMID 31695781, 2019).